PNCK (pregnancy up-regulated nonubiquitous CaM kinase)
Description:
Calcium/calmodulin-dependent protein kinase belonging to a proposed calcium-triggered signaling cascade. In vitro phosphorylates CREB1 and SYN1/synapsin I. Phosphorylates and activates CAMK1 (By similarity).
Synonyms: MGC45419; CaMK1b; BSTK3
Tractability: Small molecule: a high-quality ligand is known; it belongs to a druggable protein family. Antibody: the Human Protein Atlas places it where antibodies can reach. PROTAC: its protein half-life has been measured; a small molecule that binds it is known.
Target class: Enzyme; Transferase
Gene: Protein-coding gene on chromosome X (153,669,730 to 153,689,033, reverse strand). Ensembl gene ENSG00000130822.
Subcellular location: Cytoplasm; Nucleus
Subcellular location (Human Protein Atlas): Cytosol; Plasma membrane; Golgi apparatus
Gene Ontology:
Molecular function: calcium/calmodulin-dependent protein kinase activity; calmodulin binding; ATP binding; protein kinase activity; protein serine kinase activity
Biological process: signal transduction
Cellular component: cytoplasm; nucleus
Homologues: Orthologues: chimpanzee PNCK (99% identical), macaque PNCK (97% identical), mouse Pnck (95% identical), rat Pnck (95% identical), dog PNCK (95% identical), pig PNCK (86% identical), rabbit PNCK (86% identical), tropical clawed frog pnck (64% identical). Paralogues in human: CAMK1 (64% identical), CAMK1D (64% identical), CAMK1G (59% identical), DCLK1 (42% identical), CAMKV (40% identical), PSKH1 (40% identical), CAMK2D (39% identical), DCLK2 (39% identical), CAMK2G (39% identical), CAMK2A (38% identical), CAMK2B (38% identical), PSKH2 (37% identical), and 10 more.
Diseases named in the same sentence as PNCK in open-access papers:
PNCK is named in the same sentence as 17 diseases in open-access papers, as found by Europe PMC text mining. Sharing a sentence is not in itself a finding about the gene and the disease. The quoted sentences say what the papers report.
breast carcinoma (3 papers, 2019 to 2022). "Additionally, ectopic expression of PNCK causes trastuzumab resistance in HER-2 amplified breast cancer via PTEN-mediated process, suggesting that inhibition of PNCK may be a novel strategy to overcome drug resistance." (PMID 31839828, 2019). "Human breast cancers overexpress PNCK compared to benign breast tissues as PNCK plays an important role in mammary development." (PMID 35659630, 2022). "CamK-A/PNCK/IkBa increases the progression of breast cancer microenvironment remodeling through an enhancement in NF-κB signaling." (PMID 33050646, 2020). "In breast cancers, lncRNA CamK-A binds to PNCK, which is activated by Ca2+ in hypoxia, and IkBa, resulting in its ubiquitination via IkBa phosphorylation." (PMID 33050646, 2020). "Similarly, PNCK is up-regulated in the transformation of human breast cancer, suggesting that PNCK may be involved in mammary development and carcinogenesis." (PMID 31839828, 2019).
clear cell renal cell carcinoma (3 papers, 2019 to 2022). "Additionally, high PNCK expression is associated with poor prognosis, advanced T, N stage, and poor differentiation in clear cell renal cell carcinoma." (PMID 35535310, 2022). "Furthermore, a significant correlation between PNCK expression and Fuhrman grade, tumour size, T and N stage was observed in these clear cell renal carcinoma samples, and high levels of PNCK is an independent predictor for poor patient survival." (PMID 30621060, 2019). "For example, CaMKIγ/PNCK is overexpressed in a subset of primary breast cancers compared to benign mammary tissue, and in clear renal cell carcinoma compared to adjacent non-tumour tissues." (PMID 30621060, 2019).
nasopharyngeal carcinoma (3 papers, 2019 to 2021). A carcinoma arising from the nasopharyngeal epithelium. "PNCK was reported to promote proliferation in nasopharyngeal carcinoma cells." (PMID 33318296, 2020). "PNCK knockdown has been reported to regulate PI3K/AKT/mTOR signaling pathway and suppress growth and induce apoptosis of nasopharyngeal carcinoma cells in vitro and in vivo." (PMID 33801837, 2021). "However, the expression profile and its biological relevance of PNCK in nasopharyngeal carcinoma (NPC) have not been elucidated." (PMID 31839828, 2019).
lung adenocarcinoma (1 paper, 2022). A carcinoma that arises from the lung and is characterized by the presence of malignant glandular epithelial cells. "Furthermore, new candidate driver genes of lung adenocarcinoma, like PNCK and IP6K2 could also be found in this family." (PMID 35712480, 2022).
renal cell carcinoma (1 paper, 2020). "PNCK (Tbio) mRNA expression and activity has recently been linked to renal cell carcinoma progression and survival, breast cancer tumor microenvironment remodeling, and decreased sensitivity to chemotherapies such as temozolomide." (PMID 33205077, 2020).
tumor (12 papers, 2019 to 2025). "In this study, we demonstrated that SLC12A5 triggers ER stress to release Ca2+, thereby promoting tumor progression by activating PNCK." (PMID 36645171, 2023). "In a tumour microenvironment study, positions 355–414 and 1298–1353 of lncRNA CamK-A are bound and protected by PNCK and IκBα, which is important in tumour progression." (PMID 33803328, 2021). "Co-overexpression of HER-2 and PNCK has also been known to enhanced tumor cell proliferation and Trastuzumab resistance." (PMID 33801837, 2021). "In fact, PNCK is the most significantly overexpressed kinase in these cancers, suggestive of a tumor-specific differential need for PNCK or CaMK activity compared to normal tissue." (PMID 33205077, 2020). "Consistently, a significant reduction of tumor bioluminescence in mice inoculated with PNCK-knockdown cells compared to that of control cells." (PMID 31839828, 2019). "For instance, activation of calcium-dependent kinase PNCK, results in macrophage recruitment, angiogenesis, and tumor progression by calcium-dependent NF-κB activation." (PMID 31367490, 2019). "The bioluminescence imaging was used to evaluate the effects of PNCK knockdown on tumor growth using a xenograft animal model." (PMID 31839828, 2019). "PNCK could enhance tumor cell proliferation, which is dependent on PTEN protein phosphatase activity." (PMID 36645171, 2023). "In this study, the high expression of PNCK was detected in NPC tumor tissues and NPC cell lines." (PMID 31839828, 2019). "CamK-A is able to do so by activating the Ca2+/calmodulin-dependent kinase PNCK, leading to the phosphorylation of IκBα, which activates NF-κB, which remodels the tumor microenvironment in several ways by promoting macrophage recruitment, angiogenesis, and tumor growth." (PMID 41154428, 2025). "In addition, in vivo assay revealed that knockdown of PNCK suppressed tumor growth." (PMID 31839828, 2019). "Moreover, the caspase 3/7 activity in PNCK knockdown tumor cells was elevated in ELISA assay." (PMID 31839828, 2019). "Moreover, animal experiments revealed that PNCK knockdown suppressed tumor growth." (PMID 31839828, 2019). "Among these upregulated DEGs, PNCK, HOXA9, and HOXB8 were all reported to be related to tumor progression in several cancers." (PMID 33318296, 2020). "High expression of PNCK resulted in increased proliferation, clonal growth, cell cycle progression, and trastuzumab resistance in ERBB2-positive tumor cells." (PMID 30965637, 2019). "We conclude that PNCK plays a potential oncogenic role in NPCs by promoting NPC cell proliferation and tumor growth, a new insight into understanding the mechanisms of NPC tumorigenesis and exploring the potential therapeutic targets for NPCs." (PMID 31839828, 2019). "There was a significant reduction of tumor volume and bioluminescence imaging (BLI) signals in tumors formed by PNCK-knockdown CNE-2 cells compared to those formed by control cells." (PMID 31839828, 2019). "Similarly, the lack of PNCK significantly inhibited the tumor weight tumors at the end of this study as compared with the tumors formed by wild-type NPC cells." (PMID 31839828, 2019).
cancer (10 papers, 2017 to 2023). A tumor composed of atypical neoplastic, often pleomorphic cells that invade other tissues. "PNCK, or CAMK1b, is an understudied kinase of the calcium-calmodulin dependent kinase family which recently has been identified as a marker of cancer progression and survival in several large-scale multi-omics studies." (PMID 37235579, 2023). "Among the 148 dark kinases included in our analysis, PKMYT1 (in 17 cancers), Mitogen-Activated Protein Kinase 15 (MAPK15) in nine cancers, CaM Kinase Like Vesicle Associated (CAMKV) in 8 cancers), PNCK and STK31 (in seven cancers) were commonly upregulated." (PMID 33801837, 2021). "The understudied multi-functional CaMKs (CAMK1D, CAMK1G, CAMKK1, PNCK) are overexpressed in 12 cancers, with PNCK being overexpressed in 9 alone." (PMID 33205077, 2020). "Some of the LSA genes have been shown to be overexpressed in advanced cancers and be associated with unfavorable clinical outcomes such as SOX11, PTPRN, PNCK and HMGA2." (PMID 28427185, 2017). "Likewise, cell cycle progression was inhibited by PNCK knockdown in SLC12A5 overexpressing‐cancer cells." (PMID 36645171, 2023). "Another study has shown that the inhibition of PNCK might delay proliferation and accelerate apoptosis in cancer cells by regulating the PI3K/AKT/mTOR signaling pathway." (PMID 36645171, 2023). "Additionally, understudied kinases CAMK1D, PNCK, and NEK3 have mutations with significant pan-cancer prognostic value, with PNCK being mutated frequently in LUAD and NEK3 in COAD and READ (p < 0.05)." (PMID 33205077, 2020). "In addition, there were multiple genes induced that are involved with cell and organelle structure and function (PNCK, UBD, CDH2, HERC5) and importantly, genes associated with the prostate, AR (MMP7, CDH2, ENO2, IGFBP3) and cancer (IFIT3, IFI44L)." (PMID 29416764, 2018). "The expression of SLC6A8 exhibited the strongest positive correlation with that of ADM, GPI, NDRG1, PGK1, and PNCK, and their correlation with SLC6A8 expression in distinct cancer types were illustrated by the heatmap, respectively." (PMID 36061183, 2022). "Among these, the genes PKMYT1, PNCK, BRSK2, ERN2, and STK31 were significant in survival in five or more cancers." (PMID 33801837, 2021). "Other less understudied commonly upregulated kinases that were frequently found to be significant in survival (≥5 cancers) included the BRSK2, ERN2, PNCK, and STK31 kinases." (PMID 33801837, 2021). "In view of the pro-oncogenic role of these proteins, it is noteworthy, that G6PD, MAPK13, PNCK, SLC16A3, and SLC2A1 are among the candidate cancer genes identified by forward genetic screens in mice." (PMID 33427197, 2021).
PNCK also shares sentences with these, for which no sentence is quoted: breast tumors (1 paper); cerebral creatine deficiency syndrome (1); cerebral hypomyelination (1); Dystonia (1); Jervell and Lange-Nielsen syndrome 1 (1); leukemia (1); liver cancer (1); renal carcinoma (1); X-linked adrenoleukodystrophy (1); X-linked deafness (1).